MAP3K9 (mitogen-activated protein kinase kinase kinase 9)
Description:
Serine/threonine kinase which acts as an essential component of the MAP kinase signal transduction pathway. Plays an important role in the cascades of cellular responses evoked by changes in the environment. Once activated, acts as an upstream activator of the MKK/JNK signal transduction cascade through the phosphorylation of MAP2K4/MKK4 and MAP2K7/MKK7 which in turn activate the JNKs. The MKK/JNK signaling pathway regulates stress response via activator protein-1 (JUN) and GATA4 transcription factors. Also plays a role in mitochondrial death signaling pathway, including the release cytochrome c, leading to apoptosis.
Synonyms: MLK1; PRKE1; MEKK9
Tractability: Small molecule: a drug acting on it is in phase 2 or 3 trials; a structure with a bound ligand is known; a high-quality ligand is known; it has a high-quality binding pocket; it belongs to a druggable protein family. PROTAC: ubiquitination databases record sites on it; a small molecule that binds it is known.
Target class: TKL protein kinase group; Protein Kinase; Enzyme; TKL protein kinase MLK family; Kinase; TKL protein kinase MLK subfamily
Chemical probes: CHEMBL517743, URMC-099
Gene: Protein-coding gene on chromosome 14 (70,722,526 to 70,809,545, reverse strand). Ensembl gene ENSG00000006432.
Subcellular location (Human Protein Atlas): Nucleoli; Nucleoplasm
Gene Ontology:
Molecular function: molecular function activator activity; protein binding; protein serine/threonine kinase activity; JUN kinase kinase kinase activity; MAP kinase kinase activity; ATP binding; MAP kinase kinase kinase activity; protein kinase activity; protein serine kinase activity
Biological process: protein autophosphorylation; protein phosphorylation; MAPK cascade; positive regulation of apoptotic process
Cellular component: cytoplasm
Genetic constraint (gnomAD): Loss-of-function variants: 45 observed, 85.59 expected, observed/expected ratio (o/e) 0.53, 90% interval 0.41 to 0.67. The upper end of that interval is the gene's LOEUF score, 0.67, which puts it in group 2 of 6, group 1 being the genes least tolerant of losing a copy. Missense variants: 1,263 observed, 1,429.8 expected, observed/expected ratio (o/e) 0.88, 90% interval 0.84 to 0.93. Synonymous variants: 526 observed, 572.47 expected, observed/expected ratio (o/e) 0.92, 90% interval 0.86 to 0.99.
Homologues: Orthologues: chimpanzee MAP3K9 (99% identical), macaque MAP3K9 (99% identical), pig MAP3K9 (96% identical), mouse Map3k9 (95% identical), rat Map3k9 (95% identical), guinea pig MAP3K9 (93% identical), rabbit MAP3K9 (72% identical), dog MAP3K9 (71% identical), tropical clawed frog map3k9 (70% identical), zebrafish map3k9 (37% identical). Paralogues in human: MAP3K10 (51% identical), MAP3K21 (47% identical), MAP3K11 (38% identical), MAP3K13 (22% identical), MAP3K12 (21% identical), MAP3K20 (13% identical), TNNI3K (12% identical), TESK1 (12% identical), LRRK2 (12% identical), TESK2 (12% identical), RAF1 (12% identical), BRAF (12% identical), and 11 more.
Diseases named in the same sentence as MAP3K9 in open-access papers:
MAP3K9 is named in the same sentence as 43 diseases in open-access papers, as found by Europe PMC text mining. Sharing a sentence is not in itself a finding about the gene and the disease. The quoted sentences say what the papers report.
pancreatic cancer (7 papers, 2018 to 2023). "For example, miR-7 negatively modulates MAP3K9 expression, suppressing the proliferation and promoting apoptosis of pancreatic cancer cells via hindering the MEK/ERK signaling pathway." (PMID 32714094, 2020). "It was observed that miR-7/MAP3K9 is critically involved in pancreatic cancer progression and that miR-7 could may be a potential target for pancreatic cancer." (PMID 31602269, 2019). "Interestingly, previous studies reported that miR-1247 targeting neuroplilin 1 and neuroplilin 2 in pancreatic cancer, targeting MAP3K9 in osteosarcoma, and targeting STMN1 in NSCLC, thereby regulated tumor cells proliferation." (PMID 29793538, 2018).
melanoma (5 papers, 2014 to 2023). A malignant, usually aggressive tumor composed of atypical, neoplastic melanocytes. "Frequent somatic mutations in MAP3Ks, including MAP3K5 and MAP3K9, were identified in melanoma patients." (PMID 37692064, 2023). "There have been several studies that have investigated the role of somatic mutations in MAP2K1 and MAP2K2, and in MAP3K5 and MAP3K9 in melanoma." (PMID 37504268, 2023). "Mutations and the loss of heterozygosity of MAP3K5 and MAP3K9 in 85% and 67% of melanoma samples, respectively, suggest inactivation of these kinases." (PMID 24743024, 2014). "Some studies have also shown that targeting MAP2K1 and MAP2K2, and MAP3K5 and MAP3K9 with specific drugs can be effective at inhibiting the growth of melanoma cells in preclinical models." (PMID 37504268, 2023). "Overexpression of these mutants reduced the phosphorylation of downstream MAP kinases, while siRNA-mediated depletion of MAP3K9 in melanoma cells led to increased cell viability after temozolomide treatment, suggesting that decreased MAP3K activity acts as a pro-survival adaptation." (PMID 24743024, 2014). "Presence of mutations in three functional components of RAC pathways (Rho family proteins, MAP3K5 and MAP3K9, PREX2) strongly indicates involvement of RAC pathway in pathogenesis of melanoma." (PMID 24743024, 2014).
lung carcinoma (4 papers, 2014 to 2023). "Thus, the decrease of miR‐148a‐3p expression associated with promoter methylation can induce lung cancer metastasis by regulating MAP3K9 expression." (PMID 37521428, 2023). "Target DEGs of miR-30c in our analysis were mostly related to the anti-apoptosis of abnormal tumor cells, including MAP3K9 in lung cancer, ST6GALNAC5 in prostate cancer, CSRNP3 in clear renal cell carcinoma, ZNF703 in breast tumors, and CLSPN in brain tumors." (PMID 36700234, 2022). "Targeted genetic dependency screen is an efficient approach to identify somatic cancer alterations and was used to identify gain-of-function (GOF) mutations in lung cancer for FGFR4, MAP3K9, and PAK5 kinases." (PMID 24817905, 2014).
metastatic melanoma (3 papers, 2014 to 2021). A melanoma that has spread from its primary site to another anatomic site. "MAP3K9 is frequently mutated in metastatic melanomas, but its function remains unclear." (PMID 26120366, 2015).
osteosarcoma (3 papers, 2018 to 2022). A usually aggressive malignant bone-forming mesenchymal neoplasm, predominantly affecting adolescents and young adults. "Circ_SIPA1L1 induces osteosarcoma progression via the miR-379-5p/mitogen-activated protein kinase kinase kinase 9 (MAP3K9) pathway." (PMID 34592879, 2021).
gastric cancer (2 papers, 2022 to 2025). A primary or metastatic malignant neoplasm involving the stomach. "CircUGGT2 is overexpressed in cisplatin-resistant gastric cancer cells and can bind competitively to miR-186-3p, lifting its inhibition of MAP3K9, which promotes the proliferation, invasion, and cisplatin resistance in gastric cancer cells." (PMID 41584846, 2025).
lung adenocarcinoma (2 papers, 2023 to 2025). A carcinoma that arises from the lung and is characterized by the presence of malignant glandular epithelial cells. "Liang and the research group disclosed that miR-148a-3p hindered the advancement of lung adenocarcinoma by targeting MAP3K9." (PMID 41114868, 2025). "Interestingly, miR-148a-3p, found to be significantly down-regulated in lung tissues, can hinder lung adenocarcinoma progression by targeting MAP3K9." (PMID 38001571, 2023).
cholangiocarcinoma (1 paper, 2023). A carcinoma that arises from the intrahepatic biliary tree (intrahepatic cholangiocarcinoma) or from the junction, or adjacent to the junction, of the right and left hepatic ducts (hilar cholangiocarcinoma). "We also identified a targetable MAP3K9 mutation, in addition to oncogenic and immunological pathways hitherto not described in any cholangiocarcinoma subtype." (PMID 37095160, 2023).
demyelinating disease (1 paper, 2021). A broad group of disorders that affect the myelin sheaths that cover the neurons. "We finally validated this result in patients and found that the mRNA level of Map3k9 was decreased in peripheral blood leukocytes from patients with MOG antibody-associated demyelinating disease compared to healthy controls." (PMID 34039371, 2021).
diabetes (1 paper, 2022). "Single-nucleotide polymorphisms (SNPs) in MAP3K9 have been shown to interact with pre-menopausal obesity and diabetes." (PMID 36291149, 2022).
esophageal cancer (1 paper, 2022). A primary or metastatic malignant neoplasm involving the esophagus. "Taken together, these results demonstrated that the PCDH20 inhibited migration of esophageal cancer cells by downregulation of MAP3K9 expression, which antagonized Wnt/β-catenin signaling pathway." (PMID 36248995, 2022). "Active β-catenin, p-AKT, and p-GSK3β levels were restored in MAP3K9 overexpressing esophageal cancer cells after simultaneous stable expression of PCDH20." (PMID 36248995, 2022). "Transwell assays showed enhanced migration of esophageal cancer cells transfected with MAP3K9." (PMID 36248995, 2022). "Furthermore, we transfected MAP3K9 into esophageal cancer cell lines that stably expressed PCDH20." (PMID 36248995, 2022). "PCDH20, as an anti-tumor gene in esophageal cancer cells, had a significant effect on the migration and invasion of ESCC cells, may mediated by inhibition of the MAP3K9/AKT/β-catenin pathway." (PMID 36248995, 2022).
heart failure (1 paper, 2014). Inability of the heart to pump blood at an adequate rate to meet tissue metabolic requirements. "In addition, genes like MAP3K9 and MAP2K6 that are essential components of the mitogen-activated protein kinase signal transduction pathways have been linked to heart failure and cardiac hypetrophy are also detected." (PMID 25255322, 2014).
liver cancer (1 paper, 2022). An epithelial or non-epithelial malignant neoplasm that arises from the liver. "The function and regulation of the MAPK signaling pathway in HCC patients have been extensively studied, but whether MAP3K9 plays a key role in liver cancer, as well as its mechanisms, remained unknown." (PMID 35311629, 2022).
Obesity (1 paper, 2022). Accumulation of substantial excess body fat. "Additionally, MAP3K9 is known to have a key role in regulating the JNK pathway, and is involved in the development of obesity." (PMID 36291149, 2022).
ovarian carcinoma (1 paper, 2016). A malignant neoplasm originating from the surface ovarian epithelium. "We found three kinases (CAMK2N1, GRK2, and MAP3K9) to be KGDs in OCC models, compared to other ovarian cancer histologies such as serous ovarian cancer." (PMID 26947069, 2016).
thyroid nodule (1 paper, 2023). A small circumscribed mass in the THYROID GLAND that can be of neoplastic growth or non-neoplastic abnormality. "This study suggests that the presence of MAP3K9 mutations in both BTG and PTC lesions, along with its role in the upstream regulation of MAPK cascade, may be implicated in the development of thyroid nodules." (PMID 37692064, 2023).
vascular tumor (1 paper, 2023). "The p.Glu38del in MAP3K9 is noteworthy given its association with increased peri-vascular tumor invasion in our series." (PMID 37095160, 2023).
tumor (18 papers, 2014 to 2023). "This study found that lncRNA HCG11 was highly expressed in NPC and promoted tumor progression by regulating MAP3K9 signaling by competitively sponging miR-490-3p." (PMID 35463310, 2022). "sEV miR-7 inhibits PC cell proliferation and induces apoptosis by directly targeting MAP3K9, and miR-195 mediate tumor-suppressive effects in PC by targeting DCLK1." (PMID 34980146, 2022). "PCDH20 exerted anti-tumor effects by MAP3K9 downregulation, which suppressed AKT/β-catenin signaling in ESCC cells." (PMID 36248995, 2022). "A separate somatic MAP3K9 frameshift (p.Ser327fs) was also present in one additional tumor." (PMID 37095160, 2023). "Thus, sequestering miR-1193 by hsa_circ_0003528 promotes tumour growth through insufficient control of MAP3K9 expression, whereas inhibition of hsa_circ_0003528 suppresses cSCC tumour growth by the upregulation of miR-1193 and downregulation of MAP3K9." (PMID 34439394, 2021). "We found that MAP2K6, MAP3K5, MAP3K9, MAP3K12, RPS6KA2, RPS6KA5, and STAT1 were lowly expressed in tumor tissues; However, NFKB1, RAC1, SHC1, and TRAF2 are highly expressed compared to normal tissues." (PMID 36969076, 2023). "In this investigation, it was observed that MAP3K1, MAP3K3, MAP3K5, MAP3K10, and MAP3K15 were upregulated in HCC tumor tissues, whereas MAP3K7, MAP3K8, MAP3K9, and MAP3K11 were downregulated in tumor tissues in GSE14520." (PMID 35311629, 2022). "As a serine/threonine protein kinase, MAP3K9 functions as an upstream activator of MAPK signaling, which is involved in tumor progression." (PMID 35463310, 2022). "As reported, miR-26b-5p is a tumor suppressor and modulator in cell cycle regulation that targets different genes, including CCND2, PLOD2, JAG1, MAP3K9 and KPN2." (PMID 34488538, 2021).
cancer (13 papers, 2012 to 2025). A tumor composed of atypical neoplastic, often pleomorphic cells that invade other tissues. "The Mitogen-activated protein kinase kinase kinase 9 (MAP3K9) is implicated in numerous biological processes and diseases, including cancer." (PMID 38927885, 2024). "The SNV percentage heatmap found that MAP3K5, STAT1, and MAP3K9 have the highest single-nucleotide mutation rates in pan-cancer." (PMID 36969076, 2023). "Ocoxin also downregulates the MAPK signaling proteins implicated in cancer development, such as MAP3K9 and MAP4K3." (PMID 33669949, 2021). "From a recent study, overexpressed miR-490-5p was fatal to pharyngolaryngeal cancer cells by reducing MAP3K9 expression." (PMID 35043728, 2022). "HCG11 and miR-490-3p can compete with each other and regulate MAP3K9 signaling, providing important clues for understanding the importance of lncRNA–miRNA functional networks in cancer." (PMID 35463310, 2022).
MAP3K9 also shares sentences with these, for which no sentence is quoted: breast carcinoma (2 papers); prostate carcinoma (2); anaplastic astrocytoma (1); Anxiety (1); bacterial infection (1); brain tumors (1); breast tumors (1); Chagas disease (1); clear renal cell carcinoma (1); colorectal cancer (1); colorectal neoplasm (1); depression (1); experimental autoimmune encephalomyelitis (1); glioblastoma (1); glioma (1); infection (1); medulloblastoma (1); myocardial infarction (1); nasopharyngeal carcinoma (1); neuroblastoma (1); neurodegenerative disease (1); oligodendroglioma (1); renal carcinoma (1); serous ovarian cancer (1).